TLR9 (toll like receptor 9)
Diseases named in the same sentence as TLR9 in open-access papers (continued):
Sharing a sentence is not in itself a finding about the gene and the disease.
tumor (continued). "For instance, combining TLR7 and TLR9 agonists (1V270 and SD-101) with anti-PD1 checkpoint inhibitor activated tumor-infiltrated macrophages and induced a potent antitumor immune response, preventing primary tumor growth and metastasis in a mouse model of head and neck cancer." (PMID 34124272, 2021). "However, these pDCs are not activated, there is a lack of TLR7 and TLR9 signaling in the tumor environment, there is no production of type 1 IFN, and they have been associated with tumor growth." (PMID 33342561, 2021). "The activation of toll-like receptor 9 (TLR9) by its synthetic agonists induces the antitumor response within the innate immunity arm, generating adjuvant effects and priming the adaptive immune response elicited by checkpoint blockade during the effector phase of tumor-cell killing." (PMID 32547560, 2020). "To evaluate whether the direct effect on A20 tumor cells could also be induced by other TLR agonists currently used for intratumoral therapy, we treated A20 cells side-by-side with the TLR3 agonist poly I:C, TLR9 agonist ODN2006, or GLA-AF." (PMID 32974162, 2020). "Notably, the combination of local TLR9 and local CTLA-4 also significantly improved CD8 to Treg ratios in the untreated lesion reflecting improved mobilization of CD8s at the injected lesion, which then traffic to the left flank tumor." (PMID 31771649, 2019). "CpG-ODN signals through toll-like receptor 9 to stimulate both innate and adaptive immune responses to eliminate tumor cells to understand whether host immune response affects NHRI-HN1 cell-derived orthotopic tumor development." (PMID 31878324, 2019). "Using JAK1/2-KOs cell lines we showed that intratumoral administration of the TLR-9 agonist SD-101 was able to overcome local resistance to anti-PD-1 even in abscopal sites, and the NKTR-214 overcame resistance to anti-PD-1 in the B2M-KO tumor growth and significantly increased survival." (PMID 30400822, 2018). "Our results confirm that the expression levels of TLR7, TLR9 and constituents of TGF-β signaling, OAZ1 and P-Para were significantly altered in the tumor tissues of Smad3+/− VD-deprived mice compared to the tumor tissues of wild type VD deprived mice tumor tissues." (PMID 27456065, 2016). "Tumor tissue derived DNA treatment did not affected the genes of TLR9 MYD88 pathway." (PMID 26133168, 2015). "Although the tumor progression could not be stopped in these animals, simultaneous stimulation of TLR9 and A20 knockdown resulted in its substantial delay." (PMID 26327508, 2015). "The findings that peri-tumoral delivery of CpG-ODN is critical in DNA repair gene down-modulation in tumors but that CpG-ODN does not interact directly with the tumor cells to induce this down-modulation points to the importance of the activation of TLR9-positive cells." (PMID 23360557, 2013). "It is also not known whether possible impaired TLR9-mediated inflammation at the site of the tumor contributes to the poor prognosis in this subgroup of TNBC." (PMID 24273604, 2013). "However, there was no significant prevention of tumor development in the TLR9−/− mice, which are defective in IgG production, after immunization with the complex of hTM4SF5R2-3 peptide and Lipoplex(O)." (PMID 22427965, 2012). "However, therapeutic application of the TLR4/TLR9 agonist complex neither induced tumor apoptosis (0.15±0.04) nor attenuated tumor cell proliferation (33.1±11)." (PMID 21931823, 2011). "After binding with the ligand, TLR9 signal pathway leading to subsequent downstream activation of the NFκB, and MAPK signaling pathways, which may responsible for the proinflammatory or progrowth microenvironment of tumor." (PMID 20696081, 2010). "Indeed, TLR9 activation via CPG-ODNs could provide protection from cancer by activating dendritic cells to stimulate innate immune responses, such as enhanced natural killer-mediated tumor killing, and the subsequent adaptive T cell and humoral immunity." (PMID 38201300, 2024).
tumor (continued). "TLR9 could induce downstream signals to recruit inflammatory factors, such as IL(interleukin)-8, TGF-β, PGE2, and other immunosuppressive molecules, leading to the continuous state of inflammation, the escape of tumor immunity, and the unlimited proliferation of tumor cells." (PMID 34733783, 2021). "Though the first mechanism could lead to synergy with anti-PD1 agents due to reduced numbers of immunosuppressive PD-L1/2+ cells in the TME, such as tolerogenic myeloid cells or tumor cells, the second mechanism via TLR9 is equally, if not more likely to work in concert with PD-1 blockade." (PMID 29898788, 2018). "This could explain the lack of protection that tumor TLR9 provides in other ethnic groups." (PMID 28886076, 2017). "Therefore, we speculated that TLR9 signaling-induced endosome recycling may increase the interaction between the antigen and MHC class I molecules, resulting in IDG retention in the endosome, thereby eliciting strong anti-tumor immunity." (PMID 26215533, 2015). "Notably, the PEGylated MP7 was not cytotoxic and could enhance tumor-specific T-cell response without induction of Toll-like receptor 9 (TLR-9)-mediated innate immune response." (PMID 26153774, 2015). "CpG-ODN, being a TLR9 agonist, may rapidly stimulate T and B cells, induce Th1 cytokines [interleukin (IL)-1, IL-6, IL-12, IL-18, TNF-α and IFN-γ] and promote the maturation of antigen-presenting cells (APCs), indirectly activate immune cells and inhibit tumor proliferation." (PMID 24748977, 2014). "Finally, the mechanisms how the lack of tumor TLR9 expression results in poor prognosis are unknown." (PMID 25101078, 2014). "We examined whether the TLR9 ligand, TLR9 agonist could activate TLR9-expressing cells in vivo and analyzed the number and phenotype of splenic CD4+ T helper cells, CD8+ T cells, B cells, pDCs and NKDCs in tumor-bearing mice, 24 hours after TLR9 agonist administration (10 mg/kg body weight, s.c)." (PMID 22666458, 2012). "Encouragingly, IT administration of the anti-PD-1 mAb with the TLR9 agonist did not result in allograft rejection but stimulated the recruitment of activated CD8+ TILs into the TME and induced B16 tumor regression." (PMID 39339217, 2024). "Soluble forms of all TLRs were elevated in GC patients, with significant differences based on disease stage but not tumor type, except for serum TLR2, TLR4, and TLR9." (PMID 39451226, 2024). "Tumor antigens are primarily presented by cDC1 to CD8+ T cells; however, cDC1 does not express TLR9 and therefore cannot be activated by CpG-A." (PMID 39772003, 2024). "In contrast, approximately 67.67% of the tumor samples with high TLR9 expression showed weak PARP1 staining or no staining, and 77.77% of those with low TLR9 expression showed strong PARP1 staining (p < 0.001)." (PMID 32483468, 2020). "Thirty-seven days after tumor challenge, all mice in the PBS group had died, whereas at 90 days post-tumor implantation, 20% of mice exhibited no tumors in the OCT4 + TLR9 group (P < 0.01)." (PMID 32296581, 2020). "The tumor studies with Ifnar1ΔIEC mice and ISS DNA-treated organoids suggest that Ido1 is not induced by type I IFN or TLR9 signaling." (PMID 32444775, 2020). "In our work, TLR9 was more highly expressed in HPV+ OPSCC when compared with HPV– and p16 expression was also higher in HPV+ cell lines and tumor specimens (data not shown)." (PMID 29416610, 2018). "There was more metastasis in TLR3 expressing tumor cells, TLR4 expressing inflammatory cells but not in TLR9 expressing fibroblasts like cells." (PMID 24904578, 2014). "The expression of TLR9 in HOPE-fixed non-small lung cancer, non-malignant tissue and tumor cell lines was assessed using immunohistochemistry, confocal microscopy, in situ hybridization, RT-PCR and DNA-sequencing." (PMID 15631627, 2005).
tumor (continued). "This modulation is unlikely to reflect a direct action of CpG-ODN on IGROV-1 cells, which do not express TLR9 and do not respond to murine CpG-ODN, and instead is likely mediated by TLR9-positive cells in the tumor microenvironment directly and/or through soluble factors." (PMID 23484053, 2013). "Whether or not the absence of TLR9 in RCC is regulated by hypoxia and HIF-1 and thereby, increase the aggressive behaviour of the tumour cells also warrant further investigation." (PMID 21929816, 2011). "The tumor-nonspecific OVA SLP and the tumor-specific altered-self SLP Gp10017 were both adjuvanted with imiquimod and supplemented with IL-2, and the lymphocytic choriomeningitis virus (LCMV)-derived tumor-nonspecific Gp34 SLP18 was supplemented with TLR9 agonist CpG as adjuvant." (PMID 38167722, 2024). "Furthermore, TLR-9 agonists and IDO pharmacological inhibitors have been shown to convert Tregs into helpers of CD8 T cell responses, suggesting that Treg depletion may not be optimal in certain tumor immunotherapy settings." (PMID 22046294, 2011).
infection (396 papers, 2006 to 2025). The state of being infected such as from the introduction of a foreign agent such as serum, vaccine, antigenic substance or organism. "In the case of infection with the v1.A6 variant, modulation in TLR9 expression was also observed when PBMCs were treated with a high dose of progesterone: receptor expression increased by 1.9 times (p = 0.00331) when cells were infected with v1.A6." (PMID 41305532, 2025). "In the current study, transcriptome analyses indicated that Toll-like receptor (TLR) receptors (Tlr7, Tlr8, and Tlr9) associated with type I IFNs production were significantly upregulated after infection." (PMID 40124358, 2025). "The increased susceptibility of TLR9-deficient mice to KP infection suggests that TLR9 plays a critical role in recognizing KP DNA and initiating appropriate immune responses, with infection established via intratracheal administration." (PMID 40140770, 2025). "In 2000, TLR9 was identified as a receptor capable of recognizing and responding to unmethylated CpG dinucleotides, and since then, its role in infections caused by viruses, bacteria, protozoa, and fungi has been extensively studied." (PMID 40460068, 2025). "Ectromelia virus (ECTV), the causative agent of mousepox, has been shown to rely on TLR9 for host defense, as TLR9-deficient mice exhibited drastically increased susceptibility to infection." (PMID 40495154, 2025). "In a study on mice, both male and female TLR9 knock-out animals showed similar susceptibility to infection with mouse cytomegalovirus (MCMV)." (PMID 41516251, 2025). "The anticoagulant PROC associated positively with TLR1 and TLR9, but, with infection, became inversely correlated with TLR2, TLR5, and TLR8." (PMID 40825056, 2025). "HMGB1 acts as an endogenous damage-associated molecular pattern (DAMP) that triggers the innate immune response via binding to toll-like receptor 2 (TLR2), TLR4, and TLR9, which contributes to infection-induced sepsis caused by several pathogens." (PMID 38022511, 2023). "The impact of TLR-9 on infections caused by various species of Leishmania is variable and depends on the specific parasite species." (PMID 37111420, 2023). "Together, our results indicate that TLR9-/- mice were more susceptible to C. gattii experimental infection in comparison to WT." (PMID 36145419, 2022). "Previously, our group showed that TLR9-/- mice were more susceptible to C. gattii after 21 days of infection." (PMID 36145419, 2022). "We found that mice deficient in both TLR2 and TLR9 (Tlr2/9−/−) have decreased trabecular bone loss in response to infection compared to WT mice." (PMID 36226943, 2022). "Decreased infection-free survival was observed with the minor allele of TLR9 (rs352139) (38.2% for TC/CC versus 59.3% for TT genotypes; P-value = 0.004)." (PMID 35967300, 2022). "TLR9‐/‐ infected mice show increased susceptibility to infection marked with enhanced parasitic burden in livers and spleen when compared to WT mice, thus validating the role of the receptor in protective response against L. infantum infection." (PMID 35119120, 2022). "In fact, comparing the susceptibility of TLR2‐/‐, TLR4‐/‐, TLR9‐/‐ and C57BL/6 WT to L. major infection, TLR9‐/‐ mice are most susceptible to this infection." (PMID 35119120, 2022). "Taken together, these observations suggest that the dual loss of TLR2 and TLR9 significantly reduces reactive callus formation during infection." (PMID 36226943, 2022). "TLR9-deficient mice had a high frequency of eosinophils in the lungs in comparison to WT mice 21 days post infection, while neutrophils were more frequent in the lungs of WT infected mice." (PMID 36145419, 2022). "More recently, we demonstrated that TLR9-deficient mice were more susceptible to C. gattii hypervirulent strain R265 in an intratracheal infection model." (PMID 36145419, 2022).
infection (continued). "Different polymorphisms were identified in the TLR9 gene sequence, among which the wild type (wt) G520R polymorphism seems to be protective against infection." (PMID 34372496, 2021). "The severe spleen and brain impairment of TLR9−/− mice throughout the infection compared to WT mice indicates a greater susceptibility of TLR9-deficient mice to C. gattii." (PMID 33446850, 2021). "In order to analyze the dispersion and tissue injury caused by C. gattii in both WT and TLR9−/− mice after 21 days of infection, histological sections were made and stained with hematoxylin, eosin and Alcian blue." (PMID 33446850, 2021). "First, prior work from our laboratory in a mouse model of S. aureus catheter-associated biofilm infection also demonstrated a TLR9-independent phenotype, confirming the findings obtained during craniotomy infection." (PMID 32290861, 2020). "In the context of HIV, TLR9 1635A/G polymorphism has previously been shown to associate with HIV acquisition/infection, disease progression, CD4 counts and set point viremia." (PMID 30651082, 2019). "The participation of IFN-γ modulated by TLR9 is still unclear, since infections caused by different species of Leishmania result in different profiles." (PMID 30802247, 2019). "In this work, we observed that TLR9-/- animals are more susceptible to infection, presenting a larger lesion size in the peak of infection, and also an increase of parasite load in the peak of infection and in the chronic phase." (PMID 30802247, 2019). "Mice lacking TLR9 have an increased susceptibility to C. neoformans infection, and TLR9 appears to be required for recruitment of DCs to the site of infection." (PMID 29543719, 2018). "About physiologic relevance with proteolytic cleavage of TLR9, reduction of cleaved TLR9 would enhance the risk of infection due to TLR9 hyporesponsiveness." (PMID 29997629, 2018). "The importance of TLR2 and TLR9 in the recognition of infection with herpes simplex virus (HSV) and HSV-caused diseases has been described, but some discrepancies remain concerning the benefits of these responses." (PMID 29760708, 2018). "Similar to the low infection dose, Tlr9−/− and Stinggt/gt mice were more susceptible to ECTV infection, but both resulted in 100% mortality." (PMID 29963044, 2018). "In case of plasmacytoid dendritic cells (pDCs), the infection with HCMV was significantly associated with increased levels of TLR9." (PMID 28340580, 2017). "We propose that synergistic TLR9/IFN-γR activation of T-bet+ B cells is a mechanism underlying infection-induced autoimmune-like responses." (PMID 29101363, 2017). "Restoration of IFN-γ levels via systemic exposure to the TLR9 agonist CpG immediately prior to infection can partially attenuate Cryptosporidium susceptibility during malnutrition." (PMID 27467505, 2016). "This is the first direct assessment of Tlr9 transcriptional changes associated with M. tb host cell infection." (PMID 27055235, 2016). "A role for TLR-mediated Treg induction has also been described in murine malaria: murine Plasmodium-activated DCs induced Tregs through TLR9, and TLR9(−/−) mice had impaired activation of Tregs, associated with a partial resistance to lethal infection." (PMID 26029205, 2015). "As evidenced by the fact that infection with either L.g LRVhigh or L.g LRVlow parasites into the MyD88−/− or TLR9−/− mice were more susceptible than wild type controls regardless of the viral burden." (PMID 24801628, 2014). "TLR9 deficiency in mice infected orally with T. gondii resulted in increased susceptibility to the infection and a 50 % reduction in IFN-γ production." (PMID 23161283, 2013). "Compared to wild-type mice, resistance to primary infection and to re-challenge was similar in TLR9-deficient or TLR6-deficient mice; it was greatly increased in TLR2-deficient mice but impaired in TLR3- or TLR4-deficient mice." (PMID 23853597, 2013).